CXCR1 (C-X-C motif chemokine receptor 1)
Diseases named in the same sentence as CXCR1 in open-access papers (continued):
Sharing a sentence is not in itself a finding about the gene and the disease.
tumor (continued). "The treatment of Reparixin, the pharmacological inhibitor of CXCR1 and CXCR2, caused the significant reduction of G-MDSCs numbers, in colon adenocarcinoma HT29 xenograft tumor and colon carcinoma CT26-GM-derived subcutaneous tumor models." (PMID 37006306, 2023). "The prevention of T-cell exhaustion and tumor rejection when rechallenged suggests modification with CXCR1/2 potentiates CAR T-cell efficacy and the formation of antitumor memory." (PMID 38136398, 2023). "show that CAR-NK cells expressing an NKG2D-CAR and CXCR1 chemokine receptor augmented their migration ability toward IL-8-secreting ovarian tumors and enhanced in vivo tumor control." (PMID 35990652, 2022). "CXCR1/2 inhibitors significantly inhibited the accumulation of TANs in tumor tissues and improved the efficacy of anti-PD-1 immunotherapy in mice." (PMID 36230676, 2022). "CXCR1 has also been used to enhance migration and tumor infiltration of NK cells modified with a CAR specific for NKG2D." (PMID 35432319, 2022). "Given the high affinity of CXCR1 to IL-8, CXCR1 transduction has been tested to augment the migration and infiltration of NK cells to IL-8-secreting tumor cells." (PMID 36428748, 2022). "It has been reported that the CXCR1/CXCR2 axis regulates myeloid-derived suppressor cells (MDSCs) in the tumor environment." (PMID 35805071, 2022). "This particular modified CAR T cell treatment synergises well with ionising radiation, which enhances tumour expression of CXCR1/2 ligand IL-8." (PMID 35205725, 2022). "In general, ELR+ CXCLs/CXCR1/2 signaling promotes tumor progression while ELR- CXCLs/CXCR3-7 signaling mainly has tumor-suppressive effects." (PMID 36612163, 2022). "It was also reported that the treatment with a small-molecule inhibitor of CXCR2 and CXCR1, SX-682 (SX), sensitized tumor-bearing mice to the anti-PD1 antibody." (PMID 35664746, 2022). "The IL-8 receptors CXCR1/2 are also specifically overexpressed in BCSCs compared with bulk tumor cells, and these cells are resistant to Fas ligand-induced apoptosis." (PMID 35216080, 2022). "CXCR1 and CXCR2 are widely expressed on neutrophils, endothelial cells, cancer cells, and tumor-associated macrophages." (PMID 36072669, 2022). "Although CXCRs have been confirmed to be highly expressed in various tumor tissues by previous research, this study is the first to present the expression of CXCR1 to CXCR7 in HNSCC." (PMID 35978426, 2022). "In previous studies, CXCL8 (IL-8), as a major pro-inflammatory chemokine, mediates tumor immune escape through extracellular binding of two G-protein-coupled receptors (CXCR1 and CXCR2)." (PMID 36532065, 2022). "The targeting of CXCR1/2 reduces the neutrophil population in several cancer models and also inhibits tumor growth and metastasis." (PMID 36091114, 2022). "CXCL8, commonly known as IL-8, and its receptors CXCR1/2 are required for inflammatory cytokines activation and transportation, as well as tumor development and metastasis." (PMID 35922850, 2022). "C29 was more efficient than other commercially available CXCR1/2 inhibitors in various tumour cells." (PMID 36497191, 2022). "In pancreatic cancer, the hypoxic stressed TME stimulate TAMs to secrete IL-8 mediated by NF-κB, leading to IL-8 to increase CXCR1/2 expressing in endothelial cells and enhance tumor angiogenesis." (PMID 35493517, 2022). "For example, antagonists to CXCR4, CCR2, CCR5, and CXCR1/2 were developed to disrupt tumor invasiveness, but now have been observed to influence immune cell migration in the TME." (PMID 33603130, 2022). "By addressing specific chemokine receptors that signal via Gαi and mediate tumor cell invasion, we demonstrated that the intrinsic activities of PD-L1 were mediated by the chemokine receptors CXCR1/2, CCR2 and CCR5." (PMID 35205789, 2022). "Critically, IL-8 has been shown to have pro-tumoural effects; so, strategies that utilise IL-8, such as ectopic CXCR1/2 expression, must acknowledge the possible tumour potentiating effects." (PMID 35205725, 2022).
tumor (continued). "The increased synthesis and secretion of IL8 has wide effects on TME given the characterized expression of CXCR1 and CXCR2 receptors on cancer cells, endothelial cells, neutrophils and tumor-associated macrophages(TAMs)." (PMID 35487914, 2022). "Therapeutic agents that disrupt CXCR1/CXCR2 receptor binding with cognate ligands have been efficacious in suppressing tumor growth as shown in preclinical studies." (PMID 33603130, 2022). "After the demonstration of the anti-tumor effect C29, we aimed to evaluate the efficacy of a CXCR1/2 inhibitor in preclinical model of HNSCC as early as possible after the onset of treatment using 18F-FDG PET-CT." (PMID 34430714, 2021). "Research on overexpressing the chemokine receptor, such as CXCR1, has also been conducted for improved tumor infiltration of CAR-NK cells." (PMID 34830003, 2021). "The role of CXCR1/2 -CXCL8 interaction with cancer has been studied from different perspectives including migration of neutrophils, TAMS, and CXCR1/2+ cancer cells to tumor sites angiogenesis, and tumor stemness." (PMID 34944943, 2021). "Given the critical role of CXCR1/2 in the recruitment of neutrophils to the tumor site, attempts were undertaken to block these receptors for cancer therapy." (PMID 34201758, 2021). "In HNSCCs, CXCR1/2 signaling promotes cell proliferation and angiogenesis leading to tumor growth and metastasis." (PMID 34430714, 2021). "Then, we used a small-molecule pharmacologic CXCR1/2 antagonist to block the CXCL8 receptor in murine tumor models established with CT26 or MC38 CRC cell to determine the effect of tumor-specific CXCL8-CXCR1/2 signaling impact on tumor behavior." (PMID 34025668, 2021). "In studies using 3D cell cultures and the 4T1 mouse model of breast cancer, tumor-secreted CXCR1/2 ligands induced the formation of neutrophil extracellular traps (NETs) which block the contact of cytotoxic T cells and NK cells with tumor cells." (PMID 34944914, 2021). "In tumor tissues, relationships were observed between perforin and granzyme B on the one hand and between IL-8 and CXCR1 on the other hand." (PMID 34804993, 2021). "In concordance with its primary role as a neutrophil attractant in inflammation, in a zebrafish model of glioma, CXCL8 was found to recruit neutrophils via CXCR1 to the tumor in the very early stages of development." (PMID 34503058, 2021). "In this regard, elegant studies carried out in mouse and zebrafish model systems highlighted the relationship between the recruitment of neutrophils and tumor progression through the blocking of CXCR1 and CXCR2 by gene knockout or using CXCR1/2 inhibitors." (PMID 34201758, 2021). "When NKG2D CAR NK cell therapy was modified to include CXCR1 gene transfer, it demonstrated superior in vivo tumour control compared to NKG2D CAR NK cell alone." (PMID 34944851, 2021). "While in the tumor microenvironment, the high affinity of IL-8 to CXCR1 and CXCR2, the activation of which has been demonstrated to play an important role in tumor progression, would contribute a great deal to the malignant process." (PMID 34497832, 2021). "With the subcutaneous hypopharyngeal tumor xenograft model, it was shown that CXCR1-expressing CAR-NK cells had enhanced tumor infiltration and tumor control as compared to control CAR-NK cells." (PMID 33407739, 2021). "CXCL8 promotes tumor angiogenesis by maintaining the proliferation and activity of endothelial cells, and CXCR1 and CXCR2 are the basis of this function." (PMID 33767987, 2021). "In this regard, peripheral blood NK cells transfected with mRNA constructs encoding the chemokine receptor CXCR1 demonstrated enhanced NK cell infiltrate to the TME, with superior tumour control in mouse models of peritoneal carcinoma." (PMID 34944851, 2021). "CXCR1 depletion reduces angiogenic potential and decreases tumor growth in androgen-independent prostate cancer." (PMID 35011369, 2021).
tumor (continued). "Altogether, these findings manifest that the migration of neutrophils to tumor tissue is likely to be achieved through the chemokine CXCR1 pathway." (PMID 34185422, 2021). "Tumor-derived CXCR1/2 ligands instigated neutrophil-mediated NETosis, which shielded tumor cells from cytotoxicity." (PMID 34503058, 2021). "The signaling pathways activated by IL-8 (PI3K and phospholipase C) are stimulated through the interaction of the cytokine with CXCR1/2 that are expressed by neutrophils, monocytes, endothelial cells, astrocytes, microglia, and different types of tumor cells." (PMID 31504643, 2020). "First, a decrease in CXCR1+ cells (all viable cells or tumor cells) was observed in the majority of patients, suggesting inhibition of recruitment of CXCR1+ cells from the bloodstream into the tumor bed." (PMID 31924241, 2020). "CXCR1 and CXCR2 act as the receptors for IL-8 present on the cell surface; CXCR1 is the major receptor on tumor cells." (PMID 32471980, 2020). "Considering the characteristic expression of CXCR1 and CXCR2 on cancer cells, endothelial cells, and tumor-associated macrophages, the increased secretion of IL-8 from tumor cells has significance to the tumor microenvironment." (PMID 32655554, 2020). "Pharmacological inhibition of CXCR1 or CXCR2 represses neutrophil infiltration into tumor sites, thus resulting in repression of tumor growth." (PMID 32296583, 2020). "Antagonizing CXCR1 by CXCR1-neutralizing antibody or by the small molecule inhibitor repertaxin selectively depleted more BCSCs than bulk tumor cells in vitro." (PMID 33584277, 2020). "More broadly, Cxcr1/2 signalling has been shown to recruit pro-tumour TANs and/or G-MDSCs in a variety of mammalian cancers." (PMID 32325966, 2020). "Once again, we observed a profound effect of the CXCR1/2-targeting pepducin upon the growth of PTEN-null PC3 xenograft tumours." (PMID 32743555, 2020). "We observed that the PTENLOW and CXCR1/2HIGH tumours formed a distinct cluster or subgroup constituting 74 (52.9%) of the 140 tumours represented in this resection cohort." (PMID 32743555, 2020). "Inhibition of CXCR1/2 is able to counteract the pro-tumoral effect of the microenvironment by sensitizing OTCs to carboplatin and inducing anti-tumor immunity." (PMID 31504643, 2020). "CXCR1+ tumor cells represented, as expected, a small percentage of cells (range 0.1–9.2%) in baseline samples and were decreased at day 21 in 7/13 evaluable patients." (PMID 31924241, 2020). "The role of ELR+CXCL and their receptors-CXCR1/2 on tumor cell proliferation, angiogenesis and microenvironment adaptation following anti-angiogenic therapies was highly documented." (PMID 32775327, 2020). "Promoting neutrophil reverse migration to accelerate the resolution of inflammation by pharmacologically inhibiting Cxcr1-Cxcl8a signaling presents another approach to counteract inflammation and to restrict tumor progression." (PMID 32161595, 2020). "When SKOV-3 and MSC tumor-bearing mice were treated with reparixin, we observed a decrease in the amount of the three cytokines, suggesting that a blockade of the CXCR1/2 leads to a reduction in the expression of these chemokines." (PMID 31504643, 2020). "In vivo, administration of a CXCR1/2-targeted pepducin (x1/2pal-i3), or CXCR2-specific antagonist (AZD5069), in combination with IR to PTEN-deficient xenografts attenuated tumour growth and progression compared to control or IR alone." (PMID 32743555, 2020). "Relative to x1/2pal-con-treated tumours, treatment with the CXCR1/2-targeting x1/2pal-i3 pepducin attenuated tumour growth (34.7 ± 0.91 days; P = 0.0003), producing a comparable growth delay to radiation (3 Gy; 35.7 ± 2.008 days)." (PMID 32743555, 2020). "The migration of neutrophils toward the tumor is mainly mediated by CXC-chemokines that bind to CXCR1 and/or CXCR2." (PMID 30691207, 2019).
tumor (continued). "Antagonizing CXCR1 either by CXCR1-neutralizing antibody or by the small molecule inhibitor Repertaxin selectively depleted BCSCs than bulk tumor cells in vitro." (PMID 31681564, 2019). "The SI was superior to that of Mel202 for all tumor cells, which is in favor of a specific effect on CXCR1/2 receptors." (PMID 31410218, 2019). "The chemokines CXCL1, CXCL2, CXCL5, CXCL6, and CXCL8 secreted from tumor cells attract neutrophils in the blood to the tumor microenvironment via CXCR1 and CXCR2 on the surface of neutrophils." (PMID 30736371, 2019). "This is in line with our finding that CXCR1 expression as well as tumor development was enhanced upon tumor transplantation." (PMID 30883740, 2019). "IL-8/CXCR1/2 signaling plays an important regulatory role in the tumor microenvironment and is important for tumor progression and metastasis." (PMID 31366916, 2019). "Interleukin-8 (IL-8), also known as CXCL8, which is secreted by tumor and inflammatory cells, promotes tumor migration, invasion, angiogenesis, and metastasis by binding with its receptors, CXCR1 and CXCR2." (PMID 31684995, 2019). "For further confirmation, CXCL1-induced promotion of tumor cell migration was abolished by neutralizing antibodies against CXCR1/2—two classical chemokine receptors for CXCL1 or selective CXCR1/2 antagonist SCH527123." (PMID 31500632, 2019). "IL-8 is an important multifunctional cytokine that not only participates in various inflammatory diseases, but also mediates tumor migration, invasion and angiogenesis by binding CXCR1 and CXCR2." (PMID 31684995, 2019). "Cancer cells express the CXC receptors CXCR 1 and 2, and IL-8, the ligand for these receptors, stimulates migration and proliferation of these tumor cells." (PMID 30936780, 2019). "The relevance of targeting the ELR+CXCL/CXCR1/2 axis was assessed by correlating the intra-tumor mRNA levels of ELR+CXCL cytokines to disease free/progression free (DFS/PFS) and overall survival (OS) of the RCC and HNSCC patients." (PMID 31410218, 2019). "We next investigated the effect of Cxcr1/2 inhibition on the proliferation of tumor-initiating astrocytes." (PMID 30185911, 2018). "Inhibitors of C–X–C motif chemokine receptor 1 (CXCR1), the IL-8 receptor, and antagonistic TGFβ antibodies have been demonstrated to reduce cancer stem cell expansion and limit tumor relapse post therapy." (PMID 30111846, 2018). "Altogether, these data suggest that blocking Cxcr1/2 inhibits tumor initiation and progression of neoplastic astrocytes in vivo, further supporting a role for Cxcr1 signaling at the tumor-forming niche." (PMID 30185911, 2018). "By blocking IL-8/CXCR1/Akt signaling via CXCR1 knockdown in tumor cells, the pulmonary metastasis of OS was inhibited and the survival of OS-bearing nude mice was prolonged." (PMID 29915309, 2018). "Metastasis tumor tissues collected as of 4 weeks post-injection of CXCR1-knockdown and scrambled control Saos2-lung-M cells were immunostained for CXCR1 and p-Akt." (PMID 29915309, 2018). "After confirming the direct role of this axes in tumor cell proliferation we further examined the effect of chemical antagonist for CXCR1/2 – Reparixin-l-lysine." (PMID 30086759, 2018). "The important findings of this study are that IL-8 promotes tumor growth by both autocrine and paracrine mechanism by binding to its receptors CXCR1 and CXCR2 as deduced from protein localization by immunohistochemistry." (PMID 30086759, 2018). "Since aggressive local invasion is the hallmark of GBM, we examined the impact of antagonizing IL-8/CXCR1/2 with reparixin-l-lysine on tumor cell invasion." (PMID 30086759, 2018).
tumor (continued). "The expression of IL-8 and CXCR1 in GBM cells and expression of CXCR1 in tumor vasculature indicates a role in GBM angiogenesis." (PMID 30086759, 2018). "Here, we show that in addition to tumor cell-intrinsic roles for Cxcr1/2, this signaling pathway is also crucial for recruitment of neutrophils into the tumor-initiating microenvironment which then supports proliferation of transformed cells." (PMID 30185911, 2018). "CXCR1 is essential not only for activation and trafficking of inflammatory mediators but also for tumor progression and metastasis." (PMID 29931443, 2018). "CXCR1 promotes tumor growth, invasion, inflammation and metastasis, and the knockdown of CXCR1 will enhance the efficacy of chemotherapy." (PMID 30139993, 2018). "Blocking the IL-8/CXCR1/Akt pathway via CXCR1 knockdown inhibited the pulmonary metastasis of Saos2-lung-MSCs and prolonged the survival of tumor-bearing mice." (PMID 29915309, 2018). "CXCL8/IL-8 retains a well-known chemotactic activity for neutrophils, acting through CXCR1/2 and playing a pivotal role in the tumor microenvironment (TME)." (PMID 29953504, 2018). "We next examined the expression of Cxcl5, Ppbp, and their cognate receptor genes, Cxcr1 and Cxcr2 in tumor cells and metastasis target organs of our models." (PMID 28341702, 2017). "Analyzing membrane fractions by Western blot showed that IRIS291, IRIS292, and IRIS293 tumor cells express high level CXCR1 on their surface (upper), increased even further when cells exposed (24h) to hypoxia (middle)." (PMID 29262555, 2017). "In our search for clinically feasible approaches for inhibiting IL-8 signaling, we found reparixin, a known CXCR1/2 inhibitor, which has been reported to inhibit tumor growth and metastasis." (PMID 28947965, 2017). "All three have been implicated in tumor proliferation, angiogenesis, and metastasis via activation of multiple upstream pathways, including STAT3, CXCR1 and CXCR2, and NF-κB, respectively." (PMID 27525640, 2017). "Similar to other known paracrine molecular targets of RAS that have been shown to foster extravasation, we show that NRAS impacts tumor cell homing to the lungs likely via CXCR1/2 signaling." (PMID 28341702, 2017). "Having been researched in a series of cancers, CXCR1 shows a tight correlation with tumor angiogenesis, invasion, metastasis, and drug resistance." (PMID 27780937, 2017). "Hypoxia and/or MSCs contact exacerbates all the events, even VEGFR2 expression on ECs and CXCR1 on IRISOE tumor cells." (PMID 29262555, 2017). "Our results support a model where NRAS‐mutant, chemokine‐expressing circulating tumor cells target the CXCR1‐expressing lung vasculature and recruit CXCR2‐expressing myeloid cells to initiate metastasis." (PMID 28341702, 2017). "Abnormal expression of CXC chemokine receptor 1 (CXCR1) has shown the ability to promote tumor angiogensis, invasion and metastasis in several cancers." (PMID 27780937, 2017). "It has been reported that chemokine receptors play an important role in tumor angiogenesis, such as CXCR1 and CXCR223,24." (PMID 28959024, 2017). "Many studies have proven that chemokines and chemokine receptors are frequently associated with tumor metastases, such as CXCR4, CCR7 and CCR10 in breast and gastric cancer, CXCR1 and CXCR5 in pancreatic cancer." (PMID 28959024, 2017). "Treatment of BT474 tumor cells in vitro with (ruxolitinib + afatinib) increased the expression of the IL-8 receptors CXCR1 and CXCR2 on the cell surface." (PMID 27379204, 2016). "We show that the chemokine receptor CXCR1 is expressed by ASCs in vivo, and that in obese patients, tumour stroma is infiltrated by CXCR1-positive cells." (PMID 27241286, 2016).